PHLDB1 (pleckstrin homology like domain family B member 1)
Synonyms: KIAA0638; LL5A; FLJ00141; LL5alpha; OI23
Tractability: Antibody: the Human Protein Atlas places it where antibodies can reach. PROTAC: ubiquitination databases record sites on it; its protein half-life has been measured.
Gene: Protein-coding gene on chromosome 11 (118,606,396 to 118,658,038, forward strand). Ensembl gene ENSG00000019144.
Subcellular location (Human Protein Atlas): Cytosol; Vesicles; Cytokinetic bridge; Nucleoplasm; Plasma membrane
Gene Ontology:
Molecular function: protein binding
Biological process: basement membrane organization
Cellular component: basal cortex
Genetic constraint (gnomAD): Loss-of-function variants: 57 observed, 117.57 expected, observed/expected ratio (o/e) 0.48, 90% interval 0.39 to 0.6. The upper end of that interval is the gene's LOEUF score, 0.6, which puts it in group 2 of 6, group 1 being the genes least tolerant of losing a copy. Missense variants: 1,542 observed, 1,742.9 expected, observed/expected ratio (o/e) 0.88, 90% interval 0.85 to 0.92. Synonymous variants: 645 observed, 704.2 expected, observed/expected ratio (o/e) 0.92, 90% interval 0.86 to 0.98.
Homologues: Orthologues: chimpanzee PHLDB1 (99% identical), pig PHLDB1 (96% identical), dog PHLDB1 (96% identical), macaque PHLDB1 (95% identical), rabbit PHLDB1 (95% identical), guinea pig PHLDB1 (95% identical), rat Phldb1 (94% identical), mouse Phldb1 (94% identical), zebrafish phldb1b (59% identical), tropical clawed frog phldb1 (58% identical), zebrafish phldb1a (49% identical), Drosophila melanogaster dos (10% identical), and 1 more. Paralogues in human: PHLDB2 (33% identical), PHLDB3 (17% identical), GAB2 (11% identical), GAB1 (10% identical), GAB3 (8% identical), GAB4 (7% identical), PLEKHS1 (5% identical).
Diseases named in the same sentence as PHLDB1 in open-access papers:
PHLDB1 is named in the same sentence as 18 diseases in open-access papers, as found by Europe PMC text mining. Sharing a sentence is not in itself a finding about the gene and the disease. The quoted sentences say what the papers report.
glioma (26 papers, 2011 to 2025). A benign or malignant brain and spinal cord tumor that arises from glial cells (astrocytes, oligodendrocytes, ependymal cells). "While it is already known that the CCDC26 is a causal variant for IDHmut glioma, these findings highlight the importance of prioritizing the PHLDB1 and D2HGDH regions in future functional experiments." (PMID 40709013, 2025). "A previous report identified rs73001406 as a candidate functional variant for glioma on 11q23.3, with PHLDB1 and DDX6 as potential target genes." (PMID 33169458, 2021). "A single nucleotide polymorphism (SNP) at locus 11q23.3 (rs498872) in the near 5′-UTR of the PHLDB1 gene was recently implicated as a risk factor for gliomas in a genome-wide association study, and this involvement was confirmed in three additional studies." (PMID 23300798, 2012). "Variants of the CCDC26 and PHLDB1 genes have predominantly been associated with low grade glioma, and there is a clear correlation between these variants and IDH1 mutation status." (PMID 23236348, 2012). "It is possible that all identified SNPs (rs17748 in the 3′UTR, rs7115634, rs2236661 and rs494560 in introns) in this region affect glioma risk by modulating PHLDB1 and ARCN1 expression levels or function." (PMID 23300798, 2012). "Two separate clusters of glioma-associated SNPs were found, including the previously reported PHLDB1 locus and a novel locus (ARCN1)." (PMID 23300798, 2012). "Nevertheless, it is worth noting that the three newly identified variants (rs7115634 in ARCN1, rs2236661 and rs494560 in PHLDB1) and the rs17748 SNP contributed to a cumulative risk effect for glioma susceptibility." (PMID 23300798, 2012). "Our data strongly support PHLDB1 as a susceptibility gene for glioma, also shedding light on a new potentially candidate gene, ARCN1." (PMID 23300798, 2012). "All variants were in two known glioma regions: 11 variants in PHLDB1 (most significant rs7125115, meta P = 1.73 × 10−13, Mayo GWAS OR = 1.48) and 10 variants in D2HGDH (most significant rs71430382, meta P = 8.86 × 10−10, Mayo GWAS OR = 1.65)." (PMID 40709013, 2025). "Among multiple significant SNPs at PHLDB1 gene region, rs2236661 and rs494560 remained significantly associated with glioma risk after adjusting for rs17748 (adjusted P = 4.09×10−6 and P = 8.73×10−6, respectively), suggesting these SNPs are independent from rs17748." (PMID 23300798, 2012). "Additionally, the rs2236661, rs494560 and rs17748 in the PHLDB1 gene were statistically significantly associated with glioma risk (adjusted P = 1.06×10−5, P = 4.23×10−5 and P = 2.36×10−5, respectively)." (PMID 23300798, 2012). "The only GWAS of glioma in an East Asian population confirmed associations near TERT, PHLDB1 and RTEL1, and identified two new variants [32•]." (PMID 34817716, 2021). "Several candidate SNP studies have been conducted in East Asian populations, which have found novel association loci for glioma as well as validated those discovered in European-ancestry populations, including loci in TERC, TERT, EGFR, and PHLDB1." (PMID 34817716, 2021). "Third, variants in CCDC26 (the 8q24 locus), C2orf80 (close to IDH), LRIG1, PHLDB1, ETFA, MAML2 and ZBTB16 were associated with IDH-mutant glioma." (PMID 31842352, 2019). "Variants in CDKN2B and RTEL1 are strongly associated with high-grade glioma while variants in CCDC26 and PHLDB1 are associated with low-grade glioma." (PMID 26839018, 2016). "We found evidence for an association between two independent loci (both the PHLDB1 and the ACRN1 genes) and a predisposition for gliomas." (PMID 23300798, 2012).
glioma (continued). "For three genes (HEATR3, PHLDB1 and RTEL1) there were both expression and splicing causal effects on glioma risk, and for one gene (EGFR) there were both expression and protein abundance causal effects on glioma risk)." (PMID 39565278, 2025). "Interestingly, the authors have validated 3 White-reported glioma risk loci in the Chinese population: rs2736100 (ORrandom-effect = 1.27; 5p15.33; TERT), rs498872 (ORfixed-effect = 1.25; 11q23.3; PHLDB1), and rs6010620 (ORfixed-effect = 1.29; 20q13.33; RTEL1)." (PMID 36350002, 2022). "For example, high-grade gliomas are associated with risk variants in RTEL1, CDKN2B, and TERT, while low-grade gliomas with IDH mutation-1p/19q codeletion are associated with risk variants in CCDC26 and PHLDB1 regions." (PMID 31968687, 2020). "Furthermore, we observed a significant association between the genetic variants in LRIG1, PHLDB1, ETFA, ZBTB16 and MAML2 and the risk of IDH-mutant glioma." (PMID 31842352, 2019). "Risk variants in LRIG1, PHLDB1, ETFA, MAML2 and ZBTB16 were also associated with IDH-mutant glioma." (PMID 31842352, 2019). "In addition to the integrated phenotypic and genotypic features of glioma, many genetic studies have found that common inherited variants near several genes (TERC, TERT, EGFR, CDKN2B, PHLDB1 and RTEL1) are associated with increased risk of adult glioma." (PMID 30462709, 2018). "Similar to previously reports, we note that 3 SNPs (rs 226661, rs494560 and rs17748) in PHLDB1 gene was only strongly associated with other non-GBM gliomas but not with GBM." (PMID 23300798, 2012). "To explore the contribution of genetic variation at the 11q23.3 locus that was previously identified by GWAS and our previous replication study for gliomas, we performed mapping of this region, including the PHLDB1 gene, using a highly correlated tag SNP approach." (PMID 23300798, 2012). "Additionally, we found two novel independent SNPs (rs7115634 and 2236661) in the PHLDB1 gene and one SNP (rs494560) in the ARCN1 gene that conferred to glioma risk." (PMID 23300798, 2012). "A case-control study recruited 855 high-grade glioma patients from four different geographic regions of the US and belonging to five inherited glioma risk variants: 5p15.3 (TERT), 8q24.21 (CCDC26/MLZE), 9p21.3 (CDKN2B), 11q23.3 (PHLDB1/DDX6) and 20q13.3 (RTEL1)." (PMID 30909395, 2019). "To understand the development of adult glioma, we demonstrate that D2HGDH and PHLDB1 should be prioritized for functional studies in IDHmut tumors." (PMID 40709013, 2025). "Specifically, among adult glioma patients that do not carry a risk allele (G-allele) for rs55705857, the D2HGDH and PHLDB1 variants increased the likelihood of having a tumor that is IDHmut." (PMID 40709013, 2025). "In glioma, genome-wide association studies have identified common genetic variations in 7 genes that increase glioma risk (TERT, EGFR, CCDC26, CDKN2A, CDKN2B, PHLDB1 and RTEL1) but BRCA1 is not among them and there is no known association between BRCA1 gene and glioblastoma multiforme (GBM)." (PMID 25880076, 2015).
brain tumors (3 papers, 2015 to 2025). "While most of the genes in the locus display somatic alterations in any cancer, only a small subset are mutated in brain tumors, notably PHLDB1 and DDX6." (PMID 26610392, 2015).
glioblastoma (3 papers, 2014 to 2016). The most malignant astrocytic tumor (WHO grade IV). "A glioblastoma susceptibility locus, Phldb1 was also present in the list of MS susceptibility genes downregulated in the pEAE mouse." (PMID 27355629, 2016).
Crohn disease (1 paper, 2018). A gastrointestinal disorder characterized by chronic inflammation involving all layers of the intestinal wall, noncaseating granulomas affecting the intestinal wall and regional lymph nodes, and transmural fibrosis. "Fasting responsive genes were also regulated by variants associated to Crohn’s disease (PTGER4), Rheumatoid arthritis (PHLDB1), Lung Function (ADAM19) and with cardiac troponin (TNNT2)." (PMID 30193568, 2018).
Insulin resistance (1 paper, 2023). Increased resistance towards insulin, that is, diminished effectiveness of insulin in reducing blood glucose levels. "Putative GSK3 substrates with defective dephosphorylation in insulin resistance included S520 and S553 on PHLDB1; S350, S354, and S358 on the microtubule regulator SLAIN2; and S1036 on ASK1." (PMID 36808134, 2023). "In addition, the GLUT4 translocation-regulator PHLDB1 contained a site that was emergent in 4 models, marking PHLDB1 as a node of crosstalk for signaling pathways both attenuated and promoted in insulin resistance." (PMID 36808134, 2023).
neuroblastoma (1 paper, 2012). Neuroblastoma (NB) is the most common solid, extracranial childhood tumor. "More importantly, the SNP, which is mapped to the near 5′-UTR of PHLDB1 (Pleckstrin homology-like domain, family B, member 1) within a 101-kb LD block on 11q23.3, is frequently deleted in patients with neuroblastoma." (PMID 23300798, 2012).
Osteopenia (1 paper, 2025). Osteopenia is a term to define bone density that is not normal but also not as low as osteoporosis. "Patients lacking PHLDB1 have recurrent fractures, short stature, bowing of long bones, osteopenia, and Phldb1 knock-out mice display reduced bone content and mineralization defects." (PMID 41410595, 2025).
tumor (2 papers, 2016 to 2025). "We observed that there were statistically significant interactions between IDH tumor mutation status and CCDC26 (rs55705857), PHLDB1 (rs7125115), and D2HGDH (rs71430382) germline variants." (PMID 40709013, 2025).
PHLDB1 also shares sentences with these, for which no sentence is quoted: cancer (4 papers); astrocytomas (2); atherosclerosis (1); atopic dermatitis (1); Obesity (1); oligodendroglioma (1); ovarian carcinoma (1); pancreatic cancer (1); rheumatoid arthritis (1); Tinnitus (1).